FGFR3 (fibroblast growth factor receptor 3)
Diseases named in the same sentence as FGFR3 in open-access papers (continued):
Sharing a sentence is not in itself a finding about the gene and the disease.
head and neck cancer (10 papers, 2014 to 2025). A primary or metastatic malignant neoplasm affecting the head and neck. "FGFR3 alterations have been implicated in head and neck cancer and in vitro and in vivo studies suggest a promising role for FGF inhibition in head and neck tumors." (PMID 34051734, 2021). "In hrHPV+ head and neck cancer, the p.S249C mutation of FGFR3 was shown to be associated with poor prognosis." (PMID 32664330, 2020). "We herein describe nine head and neck carcinomas identified in our files carrying the FGFR3::TACC3 fusion in an attempt to characterize their morphological spectrum." (PMID 39387893, 2025). "Our current series is the first one devoted to morphological characterization of head and neck carcinoma harboring the FGFR3::TACC3 fusion." (PMID 39387893, 2025). "We describe nine FGFR3::TACC3 fusion–positive head and neck carcinomas affecting six males and three females aged 38 to 89 years (median, 59)." (PMID 39387893, 2025). "Increased expression of FGFR3 has been observed in various cancer types including sarcoma, multiple myeloma, breast, prostate, lung, brain, and head and neck cancers." (PMID 33626078, 2021). "More importantly, preclinical studies have demonstrated that FGFR inhibition reduced cell proliferation and increased cell apoptosis in head and neck cancer in vitro and in vivo, highlighting the potential prognostic and therapeutic role of FGFR3 in HNSCC." (PMID 29377909, 2018). "In summary, we described a series of nine head and neck carcinomas carrying an FGFR3::TACC3 fusion." (PMID 39387893, 2025). "Moreover, recurrent UBR5::ZNF423 and FGFR3::TACC3 fusions have been detected in 8.3% and 2.5% of nasopharyngeal carcinomas, another rare virally induced head and neck carcinoma type." (PMID 39387893, 2025). "However, controlled studies on the sensitivity and specificity of the FGFR3 immunohistochemistry in head and neck cancer are not available." (PMID 39387893, 2025). "However, according to these results, FGFR3/4 and CDKN2A/B could be biomarker candidates to be studied on lung and head and neck cancers." (PMID 29544535, 2018). "However, the morphology of FGFR3::TACC3-positive head and neck carcinomas has not been well studied and it is unclear if this fusion represents a random event, or if it might characterize a morphologically distinct tumor type." (PMID 39387893, 2025).
head and neck squamous cell carcinoma (10 papers, 2016 to 2025). A squamous cell carcinoma that arises from any of the following anatomic sites: lip and oral cavity, nasal cavity, paranasal sinuses, pharynx, larynx, and salivary glands. "ERK upregulation caused by increasing FGFR3 level in HNSCC (head and neck squamous cell carcinoma) cells led to an increase in FGF2 expression, which correlated with reduced sensitivity to bevacizumab." (PMID 34830951, 2021). "Here, we show that HPV-associated SNSCC exhibits mutational patterns similar to those seen in HPV-associated cervical and head and neck squamous cell carcinomas, including an APOBEC mutational signature and hotspot PI3K/FGFR3 mutations." (PMID 40500270, 2025). "Moreover, Marshallet al. showed that FGFR2 and FGFR3 are commonly expressed in head and neck squamous cell carcinoma (HNSCC) cells and are activated by autocrine FGF2." (PMID 36111743, 2022). "FGFR3 mRNA data of 522 head and neck squamous cell carcinoma (HNSCC) were retrieved from The Cancer Genome Atlas (TCGA)." (PMID 26711175, 2016). "Another study found that after cisplatin treatment intermediate and low levels of FGFR3 and FGFR4 were expressed in different head and neck squamous cell carcinoma cell lines." (PMID 39118085, 2024). "In addition to recurrent integrations in RAD51B, NR4A2, and TP63, additional genomic alterations were found in receptor tyrosine kinases, primarily FGFR2 and FGFR3, in HPV-positive head and neck squamous cell carcinoma." (PMID 27154171, 2016).
breast tumors (9 papers, 2003 to 2024). "High expression of fibroblast growth factor receptor 3 (FGFR3) is indicated in tamoxifen-resistant breast tumors by stimulating activation of the Ras/Raf/MEK1/2/ERK1/2 and PI3K/AKT/mTOR signaling pathways." (PMID 33841325, 2021). "miR-99a was strongly down-regulated in breast tumor and FGFR3 was significantly up-regulated in breast tumor." (PMID 32038996, 2019). "FGFR3 was significantly up-regulated in breast tumor according to data retrieved from TCGA and the GTEx." (PMID 32038996, 2019). "Conversely, of the 511 CSRs overexpressed in breast tumours relative to healthy breast tissue, 72 were significantly underexpressed when compared to non-breast healthy tissues, including well-established drug targets like FGFR3, CD48, and CCR3." (PMID 38306344, 2024). "According to TCGA and GTEx data, FGFR3 is significantly upregulated in breast tumours." (PMID 35785160, 2022). "An FGFR3 splice variant similar to that of FGFR3IIIS, with a deletion (bases 933–1269) overlapping that of FGFR3IIIc (bases 969–1315), has previously been described in normal breast epithelial and breast tumour cell lines." (PMID 14520460, 2003). "We retrieved the data containing 1,085 breast tumor and 291 normal control from GEPIA, it showed that FGFR3 was significantly up-regulated in breast tumor." (PMID 32038996, 2019).
CATSHL syndrome (9 papers, 2012 to 2024). "A recent study reported that Fgfr3-deficient zebrafish showed craniofacial malformations associated with bone mineralization defects, abnormal hypertrophy, and disarrangement in the growth plate, similar to human CATSHL syndrome." (PMID 35118060, 2021). "The increased stature of Fgfr3 cKO mice is consistent previous findings in conventional Fgfr3 knockout mice and patients with CATSHL syndrome." (PMID 26091072, 2015). "Since the proband’s phenotype also showed similarity to CATSHL syndrome, caused by a loss-of-function mutation in the Fgfr3 gene, except for the absence of neurological symptoms, the Fgfr3 gene was analyzed as well as the natriuretic peptide precursor C (Nppc), Npr2, and Npr3 genes." (PMID 22870295, 2012). "Although FGFR3 plays a key role in chondrogenesis, its role in the pathogenesis of cartilaginous tumors is poorly understood; indeed, although osteochondroma is observed in several members of a family with CATSHL syndrome, there have been almost no studies examining this phenotype." (PMID 26091072, 2015).
colon carcinoma (9 papers, 2010 to 2024). "Another gene associated with colon cancer was FGFR3, and the deregulated expression of the associated miRNA hsa−mir−9, only identified in Stage IV, had an important role in colon cancer progression." (PMID 31888617, 2019). "In colon carcinomas, receptor mutations are rare, but aberrant splicing causes a decrease in functional FGFR3-IIIb, accompanied by a switch to FGFR1-IIIc." (PMID 20234367, 2010). "FGFR3 mRNA overexpression is linked to poor prognosis in colon cancer." (PMID 33143664, 2020). "We observed a similar pattern of gene regulation upon FGF receptor inhibition in HCT116 colon cancer cells (which displayed loss of spindle form upon FGFR3 RNA interference or FGF receptor inhibition), implicating a conserved role of this gene cluster downstream of the FGF receptors." (PMID 21853123, 2011). "Our recent work confirmed that CD44-positive colorectal adenoma cell growth and survival depend on autocrine FGF18/FGFR3-IIIc signaling, thus indicating importance of this pathway already in precursor lesions of colon cancer." (PMID 27650542, 2016). "For instance, FGF1 and FGF2 have been shown to promote migration of intestinal epithelial cells, and specific isoforms of FGFR3 can mediate growth and migration of colon cancer cells." (PMID 21853123, 2011). "Here, we demonstrate for the first time a major impact of FGFR3 on the migration of colon tumour cells." (PMID 20234367, 2010). "Furthermore, FGF9, a high-affinity ligand for FGFR3 is expressed in a large percentage of lung, prostate, and colon cancers." (PMID 27056048, 2016).
osteoarthritis (9 papers, 2016 to 2025). A noninflammatory degenerative joint disease occurring chiefly in older persons, characterized by degeneration of the articular cartilage, hypertrophy of bone at the margins and changes in the synovial membrane. "In addition, FGFR3 participates in the regulation of other signaling associated with osteoarthritis." (PMID 40256430, 2025). "In addition, mouse studies demonstrate a protective mechanism against osteoarthritis for the FGFR3 mutation." (PMID 37280669, 2023). "For instance, the decrease in FGFR3 expression is involved in the initiation of osteoarthritis induced by mTORC1 (mechanistic target of rapamycin complex 1) activation." (PMID 40256430, 2025). "Our data provide evidence for the FGF-signaling cascade (FGFR3, FGF18, and PIK3R1) being causally involved in osteoarthritis." (PMID 34450027, 2021). "For instance, mice might develop premature osteoarthritis (OA), since a previous study showed that Fgfr3 inactivation in chondrocytes led to this outcome." (PMID 39817451, 2025). "Recent studies show that mTOR complex 1 (mTORC1) activation downregulates FGFR3 and PTHR1 in articular chondrocytes and initiates osteoarthritis." (PMID 35462909, 2022). "Moreover, Fgf21, shown to alleviate senescence, apoptosis, and ECM degradation in osteoarthritis via the SIRT1‐mTOR signaling pathway, was upregulated in the agarose encased cells, together with Fgf1 and 2, markers of human fetal growth plate cartilage, and Fgfr3, a key regulator of chondrogenesis." (PMID 40415244, 2025).
benign skin tumors (8 papers, 2012 to 2025). "In human and murine epidermis, FGF receptor 3 (FGFR3) activation causes benign skin tumours, but the consequences of FGFR3 deficiency in this tissue have not been determined." (PMID 31830366, 2020). "It has been demonstrated that one of these mutations in the extracellular domain of FGFR3, leading to the Ser249Cys substitution, can induce benign skin tumors in mouse epidermis." (PMID 31167513, 2019). "Somatic FGFR3 mutations have been detected in 40% of seborrheic keratoses (SKs) of the hyperkeratotic and acanthotic subtypes, which are very common benign skin tumors." (PMID 25505998, 2014). "The occurrence of somatic FGFR3 mutations in benign skin tumors and epithelial malignancies is caused by excessive cell proliferation and suggests a promitogenic FGFR3 effect on keratinocytes, melanocytes, and epithelial cells." (PMID 25505998, 2014). "Seborrheic keratoses and epidermal nevi, benign tumors of the skin, can also present activating mutations of FGFR3." (PMID 23902722, 2013). "The Lys650Met FGFR3 mutation has been detected in acanthosis nigricans (AC), a benign skin tumor." (PMID 31167513, 2019). "The mechanism for the high rate of somatic FGFR3 mutations in these benign skin tumors remains elusive, but UV light exposure may play a potential role." (PMID 25505998, 2014). "In the same way, in seborrheic keratoses and epidermal nevi, benign tumors of the skin very rarely progressing into malignant disease, also present high rates of activating mutations of FGFR3, suggesting a protective role of increased FGFR3 in these models, of epithelial origin." (PMID 23902722, 2013). "Several studies showed that mutations in the fibroblast growth factor receptor 3 (FGFR3) and in the 110 kDa catalytic subunit of the phosphoinositide-3-kinase (PIK3CA) are present in human and mice benign skin tumors." (PMID 23293770, 2012). "Furthermore, except for benign skin tumors, other solid epithelial tumors have been found negative for FGFR3 mutation, pointing to a specific role in bladder carcinogenesis." (PMID 33912469, 2021).
hearing loss (8 papers, 2015 to 2024). "Among the 163 upregulated genes, we did not observe a clear enrichment of Gene Ontology processes but did obtain significant enrichment of genes associated with hearing loss, including the upregulation of Otof, Tectb, Cldn11, Sall1, Cldn14, Chrna10, Esprn, and Fgfr3." (PMID 38564333, 2024). "However, the process by which they cause hearing impairment differs considerably, although, remarkably, in both FGFR3 and WHSC1 mutants, the spiral fibres fail to organise into distinct rows." (PMID 26092122, 2015). "Causative variants related to syndromic hearing loss were found in two probands (BSND and FGFR3)." (PMID 39498320, 2024).
oral squamous cell carcinoma (8 papers, 2012 to 2023). "Moreover, CPL304110 inhibited the FGFR3 variant with activating G697C mutation that was observed in 62% (44/71) of the examined oral squamous cell carcinoma (OSCC)." (PMID 38282676, 2023). "We observed expression of FGF-2 and its receptors FGFR-2 and FGFR-3 in neoplastic progression from normal through stages of epithelial dysplasia to oral squamous cell carcinoma." (PMID 26465941, 2015). "However, all observations of FGFR3 G697C were reported in a single study of oral squamous cell carcinomas (OSCC)." (PMID 26992226, 2016). "Considering these previous findings, IFI44L might be a promising agent serving as a tumor suppressor in oral squamous cell carcinoma, possibly through acting on the FRS-mediated FGFR1, FGFR3, and downstream signaling pathways." (PMID 34903206, 2021). "The FGFR3 gene was gained in 0.6% (1/179) of oral squamous cell carcinoma but no amplification was found in oral and oropharyngeal squamous cell carcinoma." (PMID 26711175, 2016). "Oral squamous cell carcinoma cells transfected with miR-100 may modify the expression of a number of oncogenes including ID1, EGR2, MMP13, and FGFR3." (PMID 23173870, 2012).
osteosarcoma (8 papers, 2003 to 2025). A usually aggressive malignant bone-forming mesenchymal neoplasm, predominantly affecting adolescents and young adults. "In conclusion, Fgfr3+ cells at the endosteum with SSC-like properties can provide a robust source of osteosarcoma-forming cells." (PMID 41027468, 2025). "This insight highlights the potential clinical significance of targeting Fgfr3+ ESCs in the context of paediatric osteosarcoma." (PMID 41027468, 2025). "During the preparation of this manuscript a soluble FGFR3 isoform has been described in human SaOS-2 osteosarcoma cells." (PMID 14520460, 2003). "Our findings that Fgfr3+ ESCs can give rise to osteosarcoma-like tumours during skeletal growth suggest that Fgfr3+ ESCs may represent the cellular origin of cortical osteosarcomas in juvenile patients." (PMID 41027468, 2025). "However, a previous study showed that knockdown of APE1 could markedly inhibit tumor angiogenesis by downregulating FGF2/FGFR3 in human osteosarcoma model." (PMID 28839218, 2017). "Regarding osteosarcoma, a study revealed low expression of FGFR-2 and FGFR-3 across standard and patient-derived osteosarcoma cells." (PMID 32984034, 2020).
seborrheic keratosis (8 papers, 2013 to 2020). A common benign skin neoplasm usually affecting older individuals. "In the context of the skin, FGFR3 is expressed in keratinocytes, and FGFR3 mutation was associated with seborrheic keratosis." (PMID 30043421, 2018). "Somatic or acquired mutations in FGFR3 have been observed in benign skin conditions like seborrheic keratosis and epidermal nevi." (PMID 26224133, 2015). "Seborrheic keratosis, despite being hyper-proliferative remain well differentiated and rather than senescence due to oncogenic signals, a positive feedback loop between FGFR3 and the transcription factor FOXN1 has been suggested to prevent malignant progression of those lesions." (PMID 28410231, 2017). "Interestingly, somatic mutations in FGFR3 have been observed in benign skin conditions such as seborrheic keratosis and epidermal nevi (but not in adjacent normal skin)." (PMID 26224133, 2015).
acute myeloid leukemia (7 papers, 2014 to 2023). Acute myeloid leukemia (AML) is a group of neoplasms arising from precursor cells committed to the myeloid cell-line differentiation. "In lung cancer, PRMT5 activity increases FGFR3 expression by repressing miR-99, and in AML (acute myeloid leukemia) PRMT5 repression of miR-29b upregulates FLT3." (PMID 32743345, 2020). "We chose 2cell lines derived from malignancies associated with genetically activated FGFR1(KG1a, 8p11-positive acute myeloid leukemia [AML]) and FGFR3 (RT-4, urothelialcarcinoma) that are also indications in which INCB054828 is currently beinginvestigated in phase 2 clinical trials." (PMID 32315352, 2020). "However, the function of FGFR3 in acute myeloid leukemia (AML) is less understood." (PMID 33584313, 2020).
brain tumors (7 papers, 2017 to 2025). "The mechanisms of FGFR activation in brain tumors vary by tumor type, but include oncogenic FGFR3 and FGFR1 fusions, FGFR1 rearrangements, and FGFR1 mutations." (PMID 28468611, 2017). "FGFR3 mRNA levels were enriched in ST-RELA showing the highest expression among EPN as well as other brain tumors." (PMID 34046693, 2021). "Moreover, gene fusions appear to be the sole recurrent oncogenic FGFR3 alteration in brain tumors." (PMID 28468611, 2017). "The rates of alterations of the FGFR1, FGFR2, FGFR3, and FGFR4 genes in brain tumor patient samples were 1%, 1.5%, 1.7%, and 0.9%, respectively, and pediatric brain tumors had among the highest levels of FGFR gene family alterations among all brain tumor databases." (PMID 40510032, 2025).
intrahepatic cholangiocarcinoma (7 papers, 2020 to 2025). A carcinoma that arises from the intrahepatic bile duct epithelium in any site of the intrahepatic biliary tree. "Across several compounds, FGFR2 fusions were most sensitive in intrahepatic cholangiocellular carcinoma (ihCC) and FGFR3 mutations showed the best responses in urothelial cancers." (PMID 36231142, 2022). "It is estimated that 10%–30% of all solid tumors are dependent on the FGFR signaling, with 6%–15% of intrahepatic cholangiocarcinoma (ICC) harboring FGFR2 fusions and arrangements, and 20% of urothelial cancers driven by FGFR3-activating mutations or fusions." (PMID 38602417, 2024).